APOE (apolipoprotein E)
Diseases named in the same sentence as APOE in open-access papers (continued):
Sharing a sentence is not in itself a finding about the gene and the disease.
atherosclerosis (continued). "The apoE-deficient mice develop extensive atherosclerotic lesions and have been regarded as excellent model for atherosclerosis research." (PMID 25628043, 2015). "In this study, we showed that dietary vitamin A deficiency significantly accelerates atherogenesis in an atherosclerosis prone, apoE−/− mouse model, despite unaffected plasma retinol and RA concentrations." (PMID 25802864, 2015). "In this study, we investigated the effects of MED on oxidized low-density lipoprotein (ox-LDL)-induced macrophage foam cell formation and activation, and on high fat diet (HFD)-induced atherosclerosis in ApoE-deficient (ApoE−/−) mice." (PMID 26045945, 2015). "Intriguingly, it has been reported that farnesyl transferase inhibitors demonstrate the ability to prevent atherosclerosis in apolipoprotein E-deficient mice, but the biology behind its action remains an open question." (PMID 25853815, 2015). "In the current study, we detected the effects of dietary flaxseed oil containing ALA-PS on atherosclerosis in apoE-KO mice and investigated the underlying molecular mechanisms." (PMID 26180602, 2015). "Endothelial-specific overexpression of caveolin-1 accelerates atherosclerosis in apolipoprotein E-deficient mice, whereas, PPARgamma1-induced caveolin-1 attenuates atherosclerosis in apolipoprotein E-deficient mice." (PMID 25756273, 2015). "We previously reported that heterozygous deficiency of perlecan results in a reduced rate of atherosclerosis in apoE null mice, suggesting that perlecan possesses pro‐atherosclerotic properties." (PMID 25626871, 2015). "For instance, administration of apelin blocks a spectrum of AngII-mediated effects on atherosclerosis in the apolipoprotein E-deficient mice through the formation of a heterodimer between the apelin and AngII receptors." (PMID 26342945, 2015). "The apolipoprotein E (ApoE) deficient (ApoE−/−) mouse was one of the first atherosclerosis models developed." (PMID 25785279, 2015). "Previous studies showed that small-molecule compounds targeting farnesyl transferase have the ability to prevent atherosclerosis in apolipoprotein E-deficient mice, but the underlying mechanism remains to be elucidated." (PMID 25853815, 2015). "RIP3-dependent necroptosis is a key driver for inflammation in atherosclerosis; RIP3 deficiency alleviates macrophage necrosis in advanced atherosclerosis lesions in atherosclerosis-prone LDL-R−/− or ApoE−/− mice." (PMID 26045969, 2015). "The current study provides clear evidence that deletion of the AR in atherosclerosis-prone apoE-deficient female mice promotes the development of atherosclerosis, as well as obesity and dyslipidemia." (PMID 25550469, 2015). "Activated platelets were shown to exacerbate atherosclerosis in ApoE deficient mice via the recruitment of monocytes and other leukocytes." (PMID 25784879, 2015). "It has been reported that supplementation of the diet with catechin, a flavanol monomer present in MOF, results in lower atherosclerosis development in apolipoprotein E-deficient mice." (PMID 24763279, 2014). "The absence of iNOS also decreases oxidative stress and protects against atherosclerosis in apolipoprotein E-deficient (ApoE−/−) mice." (PMID 25226386, 2014). "Single nucleotide variants in APOE were described as determinants for receptor interaction rates and risk factors for atherosclerosis, hypercholesterolemia or Alzheimer disease." (PMID 25064003, 2014). "On the other hand, pomegranate flower has been demonstrated to ameliorate hyperlipidemia and decrease excess cardiac lipid accumulation in Zuker diabetic fatty rats and to attenuate atherosclerosis in apolipoprotein E deficient mice." (PMID 25295067, 2014). "AD and atherosclerosis also share the common genetic risk factors, such as the ε4 allele of apolipoprotein E (APOE4)." (PMID 24478719, 2014). "Deletion of the apoE gene in animals (apoE-deficient, apoE−/−, animals) causes problems, including atherosclerosis." (PMID 24590128, 2014).
atherosclerosis (continued). "A potent proinflammatory chemokine, MCP1, is induced by AII and has been implicated in the development of atherosclerosis in the ApoE-null mouse." (PMID 24587793, 2014). "It has been shown that overexpression of HO-1 in apoE deficient mice inhibit lesion formation, whereas HO-1 deficiency is associated with accelerated atherosclerosis in apoE deficient mice." (PMID 25324785, 2014). "Apolipoprotein E-null mice on a DBA/2J genetic background (DBA-apoE) are highly susceptible to atherosclerosis in the aortic root area compared with those on a 129S6 background (129-apoE)." (PMID 24586312, 2014). "Sca-1+ progenitors within the adventitia or media can differentiate into SMCs and contribute to atherosclerosis of vein grafts in ApoE-deficient mice." (PMID 24628920, 2014). "In the present study, we investigated the possible role of IL-35 in atherosclerosis in apolipoprotein E-deficient (ApoE−/−) mice fed on a high-fat diet with or without PBA treatment." (PMID 24498194, 2014). "GSK-3β activation in the aorta apoE-deficient hyperglycemic hyperhomocysteinemic mice fed on high-fat diet correlates with advanced atherosclerosis." (PMID 25061609, 2014). "Elevation of plasma levels of EC4 in male apolipoprotein E–deficient mice with existing atherosclerosis significantly reduced apoptosis in brachiocephalic artery plaques by ~50%." (PMID 26015951, 2014). "Decreased levels of apolipoprotein E (APOE) are an additional risk factor for the development of atherosclerosis." (PMID 25064003, 2014). "To conclude, alteration of endogenous H2S by CSE gene activation was associated with reduced atherosclerosis in ApoE-deficient mice." (PMID 25397776, 2014). "In a mouse model of atherosclerosis (ApoE-deficient mice), DDAH1 overexpression ameliorated atherosclerotic lesion formation and vascular endothelial function within the aorta." (PMID 24690995, 2014). "It has been demonstrated that CD40 and ApoE double deficient mice develop reduced levels of atherosclerosis when given a normal chow diet compared with control animals." (PMID 24478772, 2014). "Deficiency in Ccl17 in ApoE−/− mice resulted in reduced atherosclerosis that was supported by immunoregulatory functions of Treg cells." (PMID 24741577, 2014). "Here, we found that IL-35 was involved in atherosclerosis in apolipoprotein E-deficient (ApoE−/−) mice." (PMID 24498194, 2014). "Recently it has been shown that both sustained and intermittent hypoxia accelerates the progression of atherosclerosis in apolipoprotein E (apoE) deficient mice." (PMID 25324785, 2014). "Studies from our laboratory have validated human studies by demonstrating that oral infection of atherosclerosis-prone ApoE−/− mice with P. gingivalis results in local oral bone loss and systemic inflammation in atherosclerotic lesions." (PMID 25010102, 2014). "Early studies performed in the apolipoprotein E (ApoE)-deficient mouse model of atherosclerosis suggested that macrophages promote atherosclerosis." (PMID 24723924, 2014). "An important role for cav‐1 in atherosclerosis has been demonstrated using a cav‐1/ApoE−/− double knockout mouse, where loss of caveolae resulted in a significant decrease in aortic plaque load." (PMID 25344475, 2014). "In ApoE-deficient mice, transplantation of Sca1+ cells that were in close proximity to the vasa vasorum to the outer layer of vein grafts enhanced atherosclerosis, contributing approximately 30% of the neointimal smooth muscle cells." (PMID 24724094, 2014). "While probucol attenuates atherosclerotic lesion development in most animal models, it promotes atherosclerosis in apolipoprotein E-deficient mice." (PMID 24810608, 2014).
atherosclerosis (continued). "The majority of murine studies with the 4F mimetic peptide have been conducted in apolipoprotein E deficient (apoE-/-) mice, a common model of hyperlipidemia associated with development of premature atherosclerosis." (PMID 25286043, 2014). "Shinozaki and colleagues have confirmed that a deficiency in Herp (an ERS-related protein) suppresses atherosclerosis in apolipoprotein E knockout mice by attenuating the inflammatory response." (PMID 25470819, 2014). "In mice, genetic deficiency of either KLF2 or KLF4 in ApoE-/- mice (which develop atherosclerotic lesions when placed on high fat diet) enhances atherosclerosis, indicating an atheroprotective role for KLF2 and KLF4." (PMID 25540650, 2014). "Studies in mice with chemokine or chemokine receptor deficient on the ApoE or LDL receptor knockout background have further confirmed their pathological roles in atherosclerosis." (PMID 25411969, 2014). "Deficiency of APN in ApoE−/− mice promotes atherosclerosis and T-lymphocyte accumulation in the atherosclerotic lesions." (PMID 24466075, 2014). "Adenovirus-mediated increase of adiponectin significantly suppresses the progression of atherosclerotic lesions in apoE-deficient mice, an animal model that develops hyperlipidemia and vascular lesions similar to human atherosclerosis." (PMID 24719717, 2014). "Treatment with monoclonal IgM antibodies against phosphorylcholine attenuated atherosclerosis in apoE-deficient mice." (PMID 25050779, 2014). "Previous results indicated that RSV suppressed atherosclerosis in hypercholesterolemic rabbits and endothelium-specific overexpression of Sirt1 decreased atherosclerosis in apolipoprotein E-deficient (apoE−/−) mice." (PMID 24378473, 2014). "Studies demonstrated that genetic deficiency of iNOS in apoE null mice would cause lighter inflammation reaction and resulted in a decrease in atherosclerosis." (PMID 24806446, 2014). "There was a robust correlation between phosphate levels and calcium-phosphate product and atherosclerosis in ApoE-deficient SNX mice." (PMID 24690995, 2014). "Some insights have also been gained through work that overexpression of the adiponectin gene protected apoE-deficient mice from atherosclerosis by reducing lesion formation in the aortic sinus." (PMID 25328285, 2014). "sEH polymorphisms are associated with an increased risk in atherosclerosis in a number of clinical studies, and treatment of apolipoprotein E knockout mice with synthesized sEH inhibitors for 8 weeks reduced atherosclerosis in these animals." (PMID 23967089, 2013). "In order to evaluate the effects of long term treatment with the preferential TR β ligand KB3495 alone or in association with atorvastatin on the development of atherosclerosis ApoE deficient mice were treated for 10 or 25 weeks." (PMID 24324578, 2013). "Complete loss of insulin signal in vascular endothelial cells aggravated atherosclerosis in endothelium-specific insulin receptor–deficient apolipoprotein E null mice." (PMID 24349318, 2013). "The angiotensin II (AngII)-infused apolipoprotein E-deficient (ApoE−/−) mouse model is widely used to study atherosclerosis and abdominal aortic aneurysm." (PMID 23469284, 2013). "ApoE gene polymorphism have been found to affect ApoE gene transcription and the serum levels of cholesterol and triglyceride, thus changing the progression of atherosclerosis, which is the main underlying pathology of CAD." (PMID 23826174, 2013).
atherosclerosis (continued). "Regarding systemic FGFR inhibition, one paper described the beneficial effect of the compound SU5402 in the inhibition of the progression of atherosclerosis in apoE-deficient mice." (PMID 24224032, 2013). "Similar to this study, administration of FTY720, an analog of myriocin, also prevents atherosclerosis in apoE-deficient mice." (PMID 23761785, 2013). "Studies have demonstrated that CD36-deficiency dramatically inhibits lesion development in ApoE-/- mice, and can also have a protective effect in late stages of atherosclerosis." (PMID 24324556, 2013). "ApoE(−/−) mice lack the lipid carrier, apolipoprotein E, and consequently display hypercholesterolemia and increased susceptibility to the development of atherosclerosis." (PMID 23840960, 2013). "Defective insulin secretion, smaller islet mass and islet inflammation have been found in atherosclerosis-susceptible B6.ApoE-/- mice compared to atherosclerosis-resistant BALB.ApoE-/- mice (C57BL/6 and BALB/cJ respectively)." (PMID 23547749, 2013). "PI3K p110γ is implicated in atherosclerosis, as its genetic deletion in ApoE−/− mice leads to reduced plaque size and impaired activation of the PI3K/Akt pathway in neointimal macrophages." (PMID 23991137, 2013). "In summary, we show that adiponectin receptors are crucial during embryonic development and that AdipoR2-deficiency slows down the progression of atherosclerosis in the brachiocephalic artery of ApoE-deficient mice." (PMID 24324556, 2013). "Further studies show that blueberry supplementation attenuated atherosclerosis by upregulating expression of the antioxidant enzymes SOD1, SOD2, GSR, and thioredoxin reductase- (TR-) 1 in ApoE deficient mouse models of atherosclerosis." (PMID 23691264, 2013). "An experimental study reported that sitagliptin improves endothelial function and reduces proinflammatory cytokines and atherosclerosis in apoE-deficient mice." (PMID 23298374, 2013). "Several of these studies have investigated effects of amlodipine in mouse atherosclerosis models with either apoE deletion or mutation." (PMID 24244746, 2013). "Recent evidence from apolipoprotein E-deficient (apoE−/−) mice shows that aging and atherosclerosis are closely associated with increased oxidative stress and DNA damage in some cells and tissues." (PMID 23385237, 2013). "One study showed that HA overexpression in the vascular tunica media promoted the development of atherosclerosis in apolipoprotein E-deficient (apoE–/–) mice." (PMID 23484050, 2013). "Meanwhile transgenic exogenous CETP expression in apolipoprotein E (apoE) or LDL receptor knock-out mice exhibit an increased susceptibility to arterial atherosclerosis." (PMID 24204732, 2013). "In fact, in Apolipoprotein E (ApoE)-deficient mice, endothelial cell-specific inhibition of NF-κB resulted in reduced development of atherosclerosis." (PMID 24113581, 2013). "In contrast, monocyte chemoattractant protein-1 (MCP-1) plays a critical role in the mobilization and infiltration of monocytes, and accelerates atherosclerosis in apoE-deficient mice." (PMID 24373412, 2013). "In this study, we now confirm and expand on our initial findings by demonstrating that ME, in an analogous fashion to the parent compound Eb, reduces oxidative stress and diabetes-associated atherosclerosis in the diabetic ApoE/GPx1 dKO mouse." (PMID 23874911, 2013). "ApoE deficient mice, an established mouse model for atherosclerosis, were treated with KB3495 and atorvastatin either alone or in combination for a period of 10 or 25 weeks." (PMID 24324578, 2013). "As cardiovascular co-morbidity such as atherosclerosis is present in >20% of cancer patients, we investigated cardiac response in pro-atherogenic ApoE-deficient mice." (PMID 23451141, 2013).
atherosclerosis (continued). "To clarify the role of vitamin D-deficiency in CVD in vivo, we generated mouse models of diet-induced vitamin D deficiency in two backgrounds (LDL receptor- and ApoE-null mice) that resemble humans with diet-induced hypertension and atherosclerosis." (PMID 23349943, 2013). "The goal of this work was to identify changes in oxidative and nitrative stress pathways and the status of the endothelinergic system during progression of atherosclerosis in ApoE-deficient mice after single and repeated exposure to ionizing radiation." (PMID 23840332, 2013). "Macrophage-derived apoE ameliorates dyslipidemia and atherosclerosis in lean and obese apoE-deficient mice, suggesting that apoE plays a role in regulating dyslipidemia." (PMID 23800102, 2013). "While exposure to acute low dose radiation can reduce atherosclerosis lesions in ApoE-deficient mice, an effect that can be interpreted as protective, it also can increase delayed cardiac fibrosis due to a pro-inflammatory state." (PMID 23840332, 2013). "The statistically significant, age-dependent and radiation-independent increase in percent lesion area is attributed to progression of atherosclerosis, which is particularly steep between 4 months and 6 months of age in the ApoE-deficient mice." (PMID 23840332, 2013). "Using ApoE deficient animals we show that atherosclerosis is reduced following treatment with KB3495." (PMID 24324578, 2013). "It is supposed that high levels of apoE increase atherosclerosis risk by stimulating hepatic VLDL production and inhibiting VLDL lipolysis." (PMID 23537337, 2013). "Although the apoE-deficient mouse model has been utilized widely in atherosclerosis research, it possesses certain drawbacks, such as a somewhat non-physiological lipoprotein profile." (PMID 24131481, 2013). "Apolipoprotein E-deficient (ApoE−/−) mice are one of the most widely used animal model of atherosclerosis and abdominal aortic aneurysm (AAA)." (PMID 23469284, 2013). "SR-BI deficiency results in increased atherosclerosis in apoE or LDL receptor KO or diet induced models of atherosclerosis." (PMID 23967310, 2013). "Our previous studies showed that dietary capsaicin improved endothelium-dependent vasorelaxation in a hypertensive rat genetic model and ameliorated atherosclerosis in apolipoprotein E deficient (ApoE-/-) mice through the promotion of PKA phosphorylation." (PMID 23607427, 2013). "In order to study the effects of combined AdipoR1 and AdipoR2 deficiency on atherosclerosis during ApoE deficiency, we first wanted to produce AdipoR1-/-AdipoR2-/- mice." (PMID 24324556, 2013). "CHOP deficiency prevents the development of atherosclerosis by reducing apoptosis and inflammation in the arteries of apoE−/− mice." (PMID 24204574, 2013). "Studies have shown that ApoE-/-Caspase-1/11-/- double deficient mice have fewer signs of atherosclerosis than ApoE-/- mice, meaning that inflammasome activation is also a key factor in the inflammatory response during atherosclerosis." (PMID 24312444, 2013). "A decreased n-6/n-3 ratio in tissues has been reported to reduce atherosclerosis due to the inhibition of systemic and vascular inflammation in apolipoprotein E-deficient mice." (PMID 23413782, 2013). "In contrast to previous studies on TLR2, when ApoE−/− mice deficient in TLR4 were infected with P. gingivalis they were paradoxically more susceptible for developing atherosclerosis, presenting with increased levels of inflammatory Th17 cells." (PMID 23880853, 2013). "We then investigated the effect of AdipoR2-ablation on the progression of atherosclerosis in apolipoprotein E deficient (ApoE-/-) mice." (PMID 24324556, 2013). "In this study, we evaluated the influence of L. major infection on the development of atherosclerosis using atherosclerosis-susceptible apolipoprotein E-deficient (apoE KO) mice." (PMID 23710353, 2013).